PTCD2P1 (pentatricopeptide repeat domain 2 pseudogene 1)
Gene: Processed pseudogene on chromosome 14 (20,524,287 to 20,525,422, reverse strand). Ensembl gene ENSG00000258456.
Diseases named in the same sentence as PTCD2P1 in open-access papers:
PTCD2P1 is named in the same sentence as 1 disease in open-access papers, as found by Europe PMC text mining. Sharing a sentence is not in itself a finding about the gene and the disease. The quoted sentences say what the papers report.
sarcopenia (1 paper, 2023). Progressive decline in muscle mass due to aging which results in decreased functional capacity of muscles. "Among deferentially expressed genes (DEGs) and the elastic net regression model, we found five common genes (TTC39DP, SLURP1, LCE1C, PTCD2P1, and OR7E109P) that discriminated between sarcopenia patients and healthy controls with a different range." (PMID 37138756, 2023).